PIN1 (peptidylprolyl cis/trans isomerase, NIMA-interacting 1)
Diseases named in the same sentence as PIN1 in open-access papers (continued):
Sharing a sentence is not in itself a finding about the gene and the disease.
cancer (continued). "Inhibition of PIN1 plays an important role in the tumorigenesis and angiogenesis of cancer, thereby providing a new great therapeutic target." (PMID 32258027, 2020). "Our recent studies demonstrate that the stability and functions of Brd4 are positively regulated by Pin1 in cancer cells." (PMID 32266261, 2020). "This specificity provides a compelling rationale for PIN1-dependent therapeutic strategies to treat MYC-dependent cancers." (PMID 32300594, 2020). "PLK1, a trigger for G2/M transition, mediates phosphorylation of Ser65 in Pin1, stabilizing Pin1 by inhibiting its ubiquitination in human cancer cells." (PMID 32296699, 2020). "Attachment of an PIN1 octaarginine sequence to the pTide fragment enhances the membrane permeable ability and inhibits the cell growth in cancer." (PMID 32258027, 2020). "Several PIN1 targeted microRNAs (miR296-5p, miR-200c, and miR-370) inhibit cancer progression by decreasing mRNA levels of PIN145–47." (PMID 32782317, 2020). "Further, cyclin D1 and Pin1 expression levels have been shown to correlate positively in such cancers, thereby indicating Pin1 as a potential tumor-promoting factor." (PMID 31884567, 2020). "Pin1 promoted cancer progression by increasing IL‐18 expression, while Pin1 knockdown impaired IL‐18‐associated proliferation and metastasis." (PMID 32347623, 2020). "In other words, suppression of such Pin1-targeting miRNAs leads to Pin1 overexpression in various cancers." (PMID 31884567, 2020). "A major flavonoid of green tea, epigallocatechin 3 gallate (EGCG) is widely known as chemo-preventive compound for cancer and one of PIN1 inhibitor." (PMID 32258027, 2020). "An increasing body of evidence shows that Pin1 serves as a poor prognostic marker for many cancers 38, 42-44." (PMID 33162791, 2020). "More development is necessary to improve efficacy and drug-likeness of Pin1 inhibitors, especially in the context of Myc-driven cancers." (PMID 33322239, 2020). "In this article, we reviewed the existing works on the dysregulation, biological function, molecular mechanism, and significance of Pin1 in cancer cells." (PMID 32296699, 2020). "Recently, PIN1 inhibitors have been developed elsewhere using structure-based drug designs and natural compounds that inhibit the activity of cancer." (PMID 32258027, 2020). "As already mentioned, PIN1 can impact on the fate of cancer cells depending on the levels and activity of relevant client tumor suppressors and proto-oncogenes." (PMID 30873382, 2019). "ATRA directly and selectively binds to and degrades active Pin1, thereby inhibiting multiple Pin1-regulated cancer driving pathways." (PMID 31867329, 2019). "Numerous reports have demonstrated Pin1 to function as a master regulator of cancer by regulating a variety of oncogenes and tumor suppressors." (PMID 30899433, 2019). "Pin1 plays a vital role in cancer development by regulating more than 40 oncoproteins and over 20 tumor suppressors, therefore promoting cancer growth and cancer stem cell tumorigenesis." (PMID 31867329, 2019). "Our previous study has also demonstrated that Pin1 regulates XBP1 that has a critical role in cancer signaling." (PMID 30783083, 2019). "We also treated HCT116 cells with ATRA, an inhibitor of Pin1 activity and expression that has been used as potential cancer therapeutic agent." (PMID 31749682, 2019). "While in normal conditions PIN1 activity ensures a homeostatic equilibrium, it appears that during pathological processes, such as inflammation and cancer, deregulated PIN1 exacerbates the diseased state." (PMID 30873382, 2019). "Pin1 expression levels are markedly increased in most cancers and the degree of elevation correlates negatively with patient outcomes." (PMID 30899433, 2019).
cancer (continued). "Although the underlying molecular mechanism has not yet been fully elucidated, it reportedly involves increased expression of prolyl isomerase Pin1 which regulates both pyruvate kinase M2 and phosphoglycerate kinase 1 in cancer cells." (PMID 30899433, 2019). "While Pin1 is overexpressed in most human cancers, it is depleted in the brains of AD patients, where it is sequestered into PHFs by binding to hyperphosphorylated tau." (PMID 31749682, 2019). "It is apparent that targeting Pin1 for therapeutics is a substantial challenge, especially due to its opposite roles in AD and cancer." (PMID 31861908, 2019). "Recent studies have underlined the pivotal role of PIN1 (peptidylprolyl cis/trans isomerase, NIMA-interacting 1) in the inverse association between cancer and AD." (PMID 31608105, 2019). "Most of the identified PIN1 inhibitors exert their anti-proliferative effect against cancer cells in a PIN1-dependent manner with a higher inhibition of cell proliferation in PIN1-expressing cells than PIN1-depleted cells." (PMID 32010690, 2019). "Like in the normal mammary gland, PIN1 acts as a fundamental regulator of stem cell features also in cancer stem cells (CSCs) of this tissue compartment." (PMID 30873382, 2019). "In cancer tissues, however, it is suggested that increased Pin1 constitutively upregulates ACC1 protein, resulting in lipogenesis and inhibition of the citric acid cycle." (PMID 30899433, 2019). "This review focuses on molecular mechanisms and cellular processes like proliferation, metabolism, and stem cell fate, that are regulated by PIN1 in physiological conditions, discussing how these are subverted in and hijacked by cancer cells." (PMID 30873382, 2019). "Current status and open questions regarding the use of PIN1 as biomarker and target for cancer therapy as well as clinical development of PIN1 inhibitors are also addressed." (PMID 30873382, 2019). "In cancer cells, it has been observed that Pin1 enhances conformational stabilization and cell death resistance capability of BCL2, an anti-apoptotic effector that in turn inhibits apoptosis via inactivation of BAX." (PMID 31614723, 2019). "New Pin1 inhibitors have also been discovered to suppress the growth of cancer cells, even the tumor-initiating cells, as Pin1 promotes the self-renewal of these stem-like cancer cells." (PMID 31867329, 2019). "Another PIN1-dependent epigenetic mechanism in cancer cells occurs through stabilization of BRD4, a member of the bromodomain and extraterminal (BET) family of proteins that interact with acetylated histones and TFs." (PMID 30873382, 2019). "These overall findings support the possibility of Pin1 serving as a therapeutic target for cancer cells, as previous studies have suggested." (PMID 30899433, 2019). "There is increasing evidence to indicate that PIN1 enhances migration and invasion of cancer cells by promoting epithelial-mesenchymal transition (EMT)." (PMID 32010690, 2019). "As a result, PIN1 plays an important role in many human diseases including Alzheimer’s disease (AD) and cancers." (PMID 32010690, 2019). "Pin1 acts as energy switch in cancer cells determining the so called “Warburg effect” or “aerobic glycolysis”, i.e., glycolysis becomes the main source of ATP also in aerobic condition." (PMID 31614723, 2019). "PIN1 function is required for several biological hallmarks of cancer, as has been described in depth." (PMID 30873382, 2019). "Pin1 is overexpressed in many different cancer types, including lung, brain, melanoma, prostate, ovary, and cervical." (PMID 31861908, 2019).
cancer (continued). "In humans, deregulation of PIN1 levels or activity has been correlated to inflammation, obesity, diabetes, cancer, and neurodegeration." (PMID 30873382, 2019). "Currently, six miRNAs (miR-140-5p, miR-200b/c, miR-296-5p, miR-370, and miR-874-3p) have been found to bind PIN1 mRNA directly and inhibit its expression in cancers." (PMID 32010690, 2019). "Knowledge about a role of PIN1 in controlling several epigenetic regulators in normal and pathological settings is growing and suggests a role for deregulated PIN1 in fostering cancer development also through epigenetic reprogramming of gene transcription." (PMID 30873382, 2019). "Increasing evidences demonstrate that Pin1 is widely overexpressed in human cancers including HCC and participates in multiple cancer-associated signaling pathways 16-19." (PMID 31367251, 2019). "Experiments have confirmed that over-expression of these miRNAs reduces PIN1 protein expression in cancer cells and reverses PIN1-mediated cellular effects, including cell proliferation, apoptosis, migration and invasion." (PMID 32010690, 2019). "ATRA-induced PIN1 degradation results in inhibition of multiple cancer-driving pathways and suppression of proliferation in APL cells in vitro and in vivo." (PMID 32010690, 2019). "In cancer cells, both these miRNAs were found to be underexpressed, allowing PIN1 to sustain tumor progression." (PMID 30723410, 2018). "Conversely, Pin1 overexpression disrupts cell cycle coordination leading to chromosome instability and cancer development." (PMID 30093655, 2018). "Pin1-targeted microRNAs (miRNAs), including miR-200b220, miR-200c31, miR296-5p221, miR-37016, and miR874-3p17, inhibit human cancer progression via directly decreasing the mRNA level of Pin1." (PMID 30158600, 2018). "Some anticancer drugs, such as sorafenib and amsacrine, induce the apoptosis of cancer cells by reversing the Pin1-mediated stability of MCL-1141,143." (PMID 30158600, 2018). "PIN1 is overexpressed in human cancers, suggesting it promotes tumorigenesis, but depending on the cellular context, it also acts as a tumor suppressor." (PMID 30723410, 2018). "Although Pin1 is an essential factor for cancer cell growth, it is dispensable for normal cell growth." (PMID 30442923, 2018). "The prolyl isomerase Pin1 is widely over-expressed or over-activated in cancers and promotes tumorigenesis." (PMID 30442923, 2018). "Participation of PIN1 in molecular pathways regulating cancer cell migration is in accordance with the identification of PIN1 substrates with an involvement in cell motility." (PMID 30314361, 2018). "Another study has identified the novel covalent Pin1 inhibitor, KPT-6566, which impairs Pin1-dependent cancer formation and metastasis, indicating that therapeutic strategy based on Pin1 inhibition is promising." (PMID 30442923, 2018). "In conclusion, Pin1 enhances the angiogenesis of multiple cancers by promoting the expression of VEGF." (PMID 30158600, 2018). "Global upregulation of microRNAs in Pin1 KO or inhibited cancer cells is also consistent with the findings that Pin1 regulates microRNA biogenesis." (PMID 30093655, 2018). "Pin1 serves as a unified hub that is exploited in cancer to simultaneously turn oncoproteins on and turn tumor suppressors off7." (PMID 30093655, 2018). "Multiple researches illuminated that Pin1 contributes to these aberrant behaviors of cancer via promoting various cancer-driving pathways." (PMID 30158600, 2018). "Pin1 CRISPR KO 231 cells failed to grow any tumors in mice, consistent with the findings that Pin1 KO mice are highly resistant to cancer development." (PMID 30093655, 2018).
cancer (continued). "The positive correlation between poor clinical prognosis of cancer patients and PIN1 overexpression is consistent with several biochemical findings." (PMID 30314361, 2018). "In cancer cells, high levels of PIN1 amplify the activation of the Akt cascade and thus enhance tumor progression." (PMID 30723410, 2018). "PIN1 can be aberrantly activated in human cancers by various mechanisms, including changes in transcription, translation, and/or post-translational modifications." (PMID 30590041, 2018). "Alone, ATO dose-dependently induced proteasome-dependent Pin1 degradation and inhibited cancer cell growth." (PMID 30093655, 2018). "The E3 ligase FBXW7 suppresses cancer by reducing multiple oncogenes, but Pin1 inactivates FBXW7 by disrupting its dimerization and promoting its self-ubiquitination." (PMID 30158600, 2018). "These processes are always aberrant in cancer that contribute to the high expression and/or overactivation of Pin1." (PMID 30158600, 2018). "For instance, cancers displaying elevated PIN1 levels include melanoma, breast, prostate, lung, ovarian, oral, and cervical tumors, to name a few." (PMID 30314361, 2018). "It is clear that Pin1 enhances the TGF-β-induced invasion and migration of cancers, but the Pin1-mediated TGF-β signal in cancer immune escape requires a deeper investigation." (PMID 30158600, 2018). "Multiple studies demonstrated that inhibition of Pin1 is effective to suppress the progression of cancers." (PMID 30158600, 2018). "Conversely, both Ser/Thr-kinase RSK2 (ribosomal protein S6 kinase 2) and COT (Cancer Osaka Thyroid) increased the binding of Pin1 to substrates leading to tumor progression." (PMID 30096758, 2018). "The development of Pin1 inhibitors has remained a challenge in the field of cancer studies as many known inhibitors of Pin1 remains unspecific enough to only block the effects of Pin1 despite a number of Pin1 inhibitors already found." (PMID 30460195, 2018). "We show that ATO directly and noncovalently binds to the common cancer signaling regulator Pin1 to block multiple cancer-driving pathways and eliminate CSCs in TNBC." (PMID 30093655, 2018). "Meanwhile, NOTCH1 induces the expression of Pin1, which consequently form a positive loop to enhance cancer cell transformation." (PMID 30158600, 2018). "PIN1 has been shown to be a proto-oncogene whose protein product regulates several proteins involved in cancer initiation and progression." (PMID 30723410, 2018). "Loss of tumor suppressors such as BRCA1 is also considered responsible for upregulated PIN1 expression in cancer." (PMID 30314361, 2018). "Pin1 is involved in almost every cancer biocapability, suggesting that it is a potential common therapeutic target." (PMID 30158600, 2018). "Wnt/β-catenin and NF-κB pathways are well-known signaling pathways in leukemogenesis through regulating cell proliferation, differentiation, or apoptosis and have been shown to be Pin1 substrates in other cancer cells." (PMID 29848341, 2018). "Taken together, these PIN1-targeting miRNAs are down-regulated in many cancers, resulting in PIN1 over-expression." (PMID 30534074, 2018). "As molecular “switch” that turns on or off enzyme activities or entire signaling pathways, Pin1 modulates many cellular functions both in physiological processes and pathological conditions (i.e., cancer, neurodegenerative and metabolic diseases)." (PMID 30096758, 2018). "The cyclin D1 activation as downstream target suggests that PIN1 coordinates different events of cell cycle, by acting as molecular timer, and that the overexpression of PIN1 in cancer leads to uncontrolled cell cycle." (PMID 30723410, 2018). "Genetic or chemical inhibition of Pin1 downregulated multiple cancer-promoting signaling pathways, leading to the inhibition of cell proliferation and colony formation capability in multiple human AML cell lines." (PMID 29848341, 2018).
cancer (continued). "Considering the antisenescence function, Pin1 and its substrates are potential targets to treat both degenerative diseases and cancers." (PMID 30158600, 2018). "Taken together, these results strongly suggest a pro-oncogenic role of Pin1 and provide a sound rationale for developing specific Pin1 inhibitors for treating cancer." (PMID 30442923, 2018). "As a result, suppression of PIN1-targeting miRNAs contributes to PIN1 over-expression in various cancers." (PMID 30534074, 2018). "This possibility is in accordance with the demonstration that PIN1 is involved in regulating various aspects of apoptosis in different biological contexts, including a variety of cancer cells." (PMID 30314361, 2018). "Although many PPIases have been identified some with an established role in cancer, only Pin1 acts distinctively and specifically on phosphorylated proteins." (PMID 30563268, 2018). "Similar to the immune regulation, Pin1 probability plays a dual role in inflammation regulation, but the cancer-promoting function of Pin1 is much more clarified." (PMID 30158600, 2018). "Pin1 has been demonstrated to have a major role in oncogenic signaling and is highly expressed in several cancers, including prostate cancer." (PMID 30563268, 2018). "This review summarized the detailed mechanisms of Pin1 in different cancer capabilities and certain Pin1-targeted small-molecule compounds that exhibit anticancer activities, expecting to facilitate anticancer therapies by targeting Pin1." (PMID 30158600, 2018). "The unique peptidyl-prolyl cis-trans isomerase Pin1 has been reported to promote tumorigenesis through upregulation of numerous cancer-driving pathways." (PMID 29848341, 2018). "Pin1 is overexpressed and/or over-activated in many human cancers, thereby disrupting the balance between oncoproteins and tumor suppressors, and by amplifying numerous cancer-driven pathways." (PMID 29848341, 2018). "The authors went on to improve the permeability of the benzothiophene class of drug to eventually yield dihydrothiazoles as a potent Pin1 inhibitor with low micromolar inhibitory activity toward cancer cell proliferation." (PMID 30460195, 2018). "Used together, ATO and ATRA cooperatively ablate Pin1, thereby blocking numerous cancer-driving pathways and inhibiting TICs and tumor growth of TNBC, similar to Pin1 KO in human cells and in orthotopic tumor models, including PDOX." (PMID 30093655, 2018). "Pin1 promotes the proliferation and suppresses the senescence of several cancer cells by preventing the E3 ligase βTrCP-induced degradation of Emi1118." (PMID 30158600, 2018). "Accordingly, KPT-6566 treatment impairs PIN1-dependent cancer phenotypes in vitro and growth of lung metastasis in vivo." (PMID 28598431, 2017). "Extensive studies showed different roles for Pin1 in physiological processes and pathological conditions such as cancer and neurodegenerative diseases." (PMID 28426725, 2017). "Pin1, a peptidyl prolyl isomerase, is an enzyme that is crucial for diverse cancer developmental processes including proliferation, apoptosis, and migration." (PMID 29050342, 2017). "Here we find that miR-140-5p inhibits HCC by directly targeting Pin1 to block multiple cancer-driving pathways." (PMID 28383568, 2017). "A central common signaling mechanism in cancer is proline-directed phosphorylation, which is further regulated by the unique proline isomerase Pin1." (PMID 28262728, 2017). "Taken together, our data show that miR-140-5p has potent anti-tumor activity against HCC through targeting Pin1 to block multiple cancer pathways in vitro and in vivo." (PMID 28383568, 2017).